TNF (tumor necrosis factor)
Diseases named in the same sentence as TNF in open-access papers (continued):
Sharing a sentence is not in itself a finding about the gene and the disease.
metabolic syndrome (continued). "Among the pathways, the AGE-RAGE, NF-κB, HIF-1, IL-17, TNF, FoxO, and PPAR signalling pathways are closely related to the treatment of dyslipidemia with HLJDD." (PMID 36061816, 2022). "Researchers recently discovered that tumor necrosis factor-alpha (TNF-α), which is a proinflammatory cytokine and a crucial contributor to various metabolic syndromes, modulates the expression of MBNL." (PMID 34948025, 2021). "Acute exercise increased the plasma concentration of TNFα, intercellular adhesion molecule ICAM1, PGE1, PGE2 and the newly detected 16-hydroxypalmitic acid (16-HPAL) in metabolic syndrome patients." (PMID 32646062, 2020). "Inflammation markers (IL-6, TNF-a and CRP) correlate positively with weight, and metabolic syndrome is related to pro-inflammation and coagulation." (PMID 33108241, 2020). "Inflammation markers (IL-6, TNF-a and CRP) correlate positively with weight, and the metabolic syndrome is related to pro-inflammation and coagulation." (PMID 33108241, 2020). "The expression of p-IRS(ser307) and TNF-α in WAT and liver tissue were measured, and dyslipidemia, a major characteristic of peripheral-IR, was confirmed by blood serum biochemical analysis to determine the effect of EFAD on peripheral tissue." (PMID 31212845, 2019). "The results revealed that high CP infection rate, dyslipidemia and the overexpression of inflammatory factors, such as IL-6, hs-CRP and tumor necrosis factor-ɑ (TNF-α), can be commonly found in patients with CHD." (PMID 31088358, 2019). "Isoflavone (genistein) exerted benefits by attenuating serum dyslipidemia (TC level in serum), lipid peroxidation, oxidative stress (GSH activity), inflammatory stress (TNF-α level), and hepatic fibrosis." (PMID 30441755, 2018). "Our study confirmed previous reports of the existence of dyslipidemia (enhanced TG, TC, LDL-C, apoB, Lp(a), apoCIII and lower HDL-C and apoAI) and inflammation (increased TNF-α and hs-CRP) in CHD patients." (PMID 30053815, 2018). "The aims of the current study were to explore maternal circulating values of TNF-α, adiponectin and the adiponectin/TNF-α ratio in women with GDM compared with normal pregnancy and their relationships with metabolic syndrome biomarkers." (PMID 29387323, 2018). "However, in a study of human subjects with metabolic syndrome, 60-day supplementation with cranberry juice did not cause significant changes in the levels of pro-inflammatory cytokines: TNF-alpha, IL-1 and IL-6, despite an improvement of some cardiovascular risk factors." (PMID 28261001, 2017). "Ferretin, hs-CRP, IL-6, TNF-α, and LDL have all been shown to be elevated in those with metabolic syndrome." (PMID 29099041, 2017). "EWH also prevented the TNF-α-mediated induction of the pro-inflammatory enzyme COX-2, a molecule that contributes to the pathologic complications of metabolic syndrome." (PMID 28972997, 2017). "A systemic pro-inflammatory and pro-coagulating state, illustrated by elevated levels of inflammatory markers such as IL-1, IL-6, TNF, and CRP, was reported among individuals with metabolic syndrome." (PMID 26964045, 2016). "The plasma markers of this phenotype included: hyperglycemia, dyslipidemia and elevated plasma levels of ALT, leptin, TNFα and TLR2 and TLR4 activators." (PMID 26761430, 2016). "Many adipose-produced inflammatory molecules, including TNF-α, IL-6, IL-1, serum amyloid A (SAA) and adiponectin, and the number of adipose macrophages also play an important role in the development of dyslipidemia." (PMID 24733068, 2014). "Patients with metabolic syndrome often present with higher levels of systemic inflammatory markers such as CRP, TNF-α, Fibrinogen and IL-6, and these markers are also increased in the blood of COPD patients." (PMID 22701684, 2012). "These cytokines, primarily Tumor Necrosis Factor-α (TNF-α) and IL6, can directly induce inflammation in cardiovascular tissues, as well as activate the HPA axis, which in turn can lead to metabolic syndrome." (PMID 20029624, 2009).
metabolic syndrome (continued). "A systematic review with meta-analysis showed that consuming flaxseed products significantly reduced inflammatory cytokine IL-6 (rather than TNF-α) in dyslipidemia patients." (PMID 40507062, 2025). "Elevated levels of IL-1, IL-6, and TNF-α in LPP may impair TG clearance by inhibiting lipoprotein lipase activity and reducing apoprotein-E levels, thus contributing to dyslipidemia." (PMID 40568287, 2025). "This study showed associations between dietary factors involved in the methylation of TNF-α and differential protein expression in the non-obese and obese groups, and these were related to metabolic syndrome." (PMID 38542788, 2024). "In contrast, the study conducted by Inge Boers, investigating the Paleo diet, showed no significant impact on hs-CRP and TNF-a levels in individuals with metabolic syndrome during a 2-week intervention period." (PMID 38476230, 2024). "Based on the information provided, our study aims to measure the levels of TNF-α in the blood of overweight and obese people in the North-Eastern states of India, both with and without metabolic syndrome." (PMID 39149648, 2024). "Several studies have established a connection between TNF-α levels and metabolic syndrome, regardless of other variables." (PMID 39149648, 2024). "We further compared estimated marginal means of TNF-α DNA methylation with frequency of food consumption in subjects with and without metabolic syndrome." (PMID 38542788, 2024). "Furthermore TNF-α (p<0.001), oxLDL/LDL (p<0.001) and oxLDL/high-density lipoprotein (HDL) (p=0.016) increased significantly with the increase of metabolic syndrome components." (PMID 37529617, 2023). "Additionally, a positive significant correlation between TNF-α, ROS, NEAT, caspase-3 and dyslipidemia." (PMID 37531036, 2023). "Furthermore, a significant correlation between femoral artery tunica intima injury and AGEs/ET-1/TNF-α/NOS axis, dyslipidemia, and glycemia was also demonstrated." (PMID 36830898, 2023). "Further adjustment for the duration of HS, metabolic syndrome, IR, serum fibrinogen levels, and the use of TNF-α inhibitors did not change these results." (PMID 37189824, 2023). "The results have suggested that GXNT could regulate dyslipidemia, improve heart function, and inhibit the levels of ox-LDL, CRP, TNF-α, IL-1β, SOD, MDA, vWF, and ET-1, as well as platelet aggregation." (PMID 35935588, 2022). "Among female participants, TNF-α increased in groups of high total cholesterol and dyslipidemia; MCP-1 remained unchanged in the group of low HDL-C but not in other groups." (PMID 36032093, 2022). "Furthermore, obvious amelioration in dyslipidemia (lower triglycerides, total cholesterol and higher HDL) and decreased inflammatory markers (TNF-α and IL6) levels have been noticed after administration of AD-MSCs treated with OXA." (PMID 35083338, 2022). "In another study, 12 weeks of aerobic exercises did not change the expression of the TNF-α gene in women with metabolic syndrome." (PMID 36004368, 2022). "The observed lack of a significant effect of CPAP on TNF-a is in line with theories proposing that OSA represents a manifestation of the metabolic syndrome." (PMID 36013431, 2022). "Furthermore, the TNF-α and IL-6 levels were decreased in the CCL4 antibody-treated group compared with those in the IgG-treated metabolic syndrome group." (PMID 33968046, 2021). "A lot of inflammatory molecules, synthesized by adipose tissues such as: IL-1, TNF-α, IL-6, adiponectin, serum amyloid A (SAA), and macrophages, could play an important role in the development of dyslipidemia." (PMID 33584134, 2021). "Furthermore, systemic inflammation, indicated by serum TNF-α and IL-6 levels, was also decreased by CCL4 inhibition in type 2 DM and metabolic syndrome mouse models in this study." (PMID 33968046, 2021).
metabolic syndrome (continued). "In patients with acute ischemic stroke and metabolic syndrome, measures of arterial stiffness (carotid–femoral PWV and aortic augmentation index) and inflammatory cytokines (TNF-α and IL-6), along with CRP, were increased compared to patients with acute ischemic stroke without metabolic syndrome." (PMID 34202323, 2021). "Our previous studies have shown that KD can significantly inhibit the levels of serum leptin, free fatty acids, tumor necrosis factor (TNF)-α and plasminogen activator inhibitor-1, and increase the expression of serum adiponectin in rats with metabolic syndrome." (PMID 34122092, 2021). "Also, the results of the present study suggested that nano-curcumin supplementation significantly decreases serum concentrations of TNF-a, IL-6, MDA, and hs-CRP in subjects with metabolic syndrome." (PMID 32256716, 2020). "From this perspective, the absence of differences in the levels of IL-6 and TNF-α among the studied groups can be explained by the crossover effects of the presence of schizophrenia and metabolic syndrome." (PMID 33066473, 2020). "KEGG pathway analysis showed that the DE mRNAs were significantly enriched in pathways related to non-alcoholic fatty liver disease (NAFLD), glycerophospholipid metabolism, TNF signaling, and WNT signaling, which are all related to inflammatory processes and dyslipidemia." (PMID 32392180, 2020). "The neutralization of either CX3CL1 or CCL2 activity on HUAEC again markedly reduced TNFα-induced leukocyte adhesion in the metabolic syndrome group, but not in the control group." (PMID 31109070, 2019). "Various inflammation markers including NFκβ, TNFα, interleukin-6 (IL-6), monocyte chemoattractant protein (MCP-1), visfatin, resistin, leptin and adiponectin have been identified in the metabolic syndrome pathogenesis." (PMID 31462242, 2019). "Pathway No. 12 (Visceral fat deposits and the metabolic syndrome) is a pathway related to the glucocorticoid receptor, which will activate/inactivate the lipoprotein lipase, TNF-alpha, and insulin resistance." (PMID 29379041, 2018). "Therefore, the aims of the current study were to explore maternal circulating values of TNF-α, adiponectin and the adiponectin/TNF-α ratio in Iranian women with GDM compared with normal pregnancy and their relationships with metabolic syndrome biomarkers." (PMID 29387323, 2018). "Chedraut and colleagues found that cytokine levels (IL-6 and TNF-α) did not correlate with hot flash scores of the menopause-specific quality of life questionnaire in postmenopausal women with metabolic syndrome." (PMID 28846735, 2017). "There was an increase of TNF-α in patients with dyslipidemia, but because of data limitation we were not able to conduct further analysis stratified by the lipid metabolism of included women." (PMID 27764100, 2016). "The median concentration of IL-1β and TNFα in patients with metabolic syndrome was elevated when compared with patients without metabolic alterations." (PMID 26101459, 2015). "vWF and TNF-α compared to subjects without metabolic syndrome; in CEI group with metabolic syndrome IL-6, TNF-α and v-WF were more positively and significantly related to AIx compared to subjects without metabolic syndrome." (PMID 24571954, 2014). "In a study of 362 children, low serum TNF-α levels did not correlate with metabolic syndrome or BMI." (PMID 23984304, 2013). "The aim of this study is to establish interactions between the GLP-1 plasma levels and metabolic syndrome clusters and adipokines profile (leptin, adiponectin, resistin) and proinflammatory cytokines (TNFα, IL-6, IL1β, IL-17) in diabetic subjects with or without MAFLD." (PMID 41683648, 2026). "Nevertheless, rs1800629 has been previously reported to modulate the expression of key components within the inflammatory signaling cascade, which could influence the production of pro-inflammatory cytokines such as IL-6, TNF-α, IFN-γ, particularly in patients with metabolic syndrome." (PMID 40881695, 2025).
metabolic syndrome (continued). "Mechanisms such as tumor necrosis factor-alpha (TNF-α)-mediated inhibition of lipoprotein lipase, low lipoprotein activity, and the presence of antibodies to lipoprotein lipase found in patients with SLE have been suggested to contribute to the pathophysiology of dyslipidemia in SLE." (PMID 39981087, 2025). "In another study, TNF-α and IL-6 concentrations and myeloperoxidase activity were higher (whereas catalase and superoxide dismutase activities were lower) in consumers with a high intake of ultra-processed food (UPF) with metabolic syndrome than in those with a low intake of UPF." (PMID 38542788, 2024). "Similarly, cranberry juice (700 mL/day for 60 days) in patients with metabolic syndrome reduced lipid peroxidation and protein oxidation levels but did not reduce TNF-α, IL-1, and IL-6." (PMID 38752013, 2024). "Pro-inflammatory cytokines, such as tumor necrosis factor alpha (TNF-α) or interleukin-6 (IL-6), are elevated in the serum of metabolic syndrome patients, and an increased level of pro-inflammatory cytokines may play an essential role in the pathogenesis of the syndrome." (PMID 35888020, 2022). "While TNF‐α appears to be more involved in the mechanism and progression of the metabolic syndrome (e.g., reduced insulin sensitivity through an increase in JNK1/2 activation), IL‐6 is likely only a marker of metabolic syndrome since it has been shown to increase lipolysis and fat oxidation." (PMID 35312183, 2022). "Adipose tissue can synthesize and secrete important adipose cytokines such as LP, TNF-α, IL-6, and ADP; participate in the regulation of glucose metabolism, lipid metabolism, and inflammation; and play a key role in the occurrence and development of metabolic syndrome." (PMID 34422044, 2021). "Some recent trials have showed that inulin supplementation lessens LPS and TNF-α in T2DM, and limits presentation of metabolic syndrome (MetS)." (PMID 33671569, 2021). "EPA and DHA, for example, have anti-inflammatory properties that may help curtail metabolic syndrome and have been shown to consistently lower C-reactive protein, tumor necrosis factor (TNF), and interleukins in healthy, non-obese individuals." (PMID 32796608, 2020). "In addition, among patients without dyslipidemia, levels of IP-10 and TNF-α were significantly correlated with CD4CD38HLDR+ cells, while levels of MIP-1-α were correlated with CD8CD38HLDR+ cells in patients with normal lipids’ levels." (PMID 29997625, 2018). "As TNF-α is a substrate for ADAM19, we hypothesise that the shedding of TNF-α by the ADAM19 metalloproteinase domain potentially exacerbates the pathogenesis of the metabolic syndrome." (PMID 28265178, 2017). "In this paper, authors hypothesize that, due to its unique TNF-α signal modulatory activity and antioxidative property, azelnidipine may be a promising DHP for targeting diabetes and cardiovascular diseases in hypertensive patients with metabolic syndrome." (PMID 26881016, 2016). "However, clinically significant dyslipidemia has been occasionally reported in patients receiving TNF-α antagonists, but this is not a common issue in clinical practice." (PMID 25654080, 2015). "An increase in hypothalamic GFAP and TNF-α in our study suggests that an obesogenic diet induces a shift in astrocytes towards astrogliosis, characterized by the production of inflammatory cytokines, regardless of the severity of the metabolic syndrome-like phenotype." (PMID 41305664, 2025). "They show that people who are overweight (Group 2) or obese without metabolic syndrome (Group 3) have higher BMI, WHR, neck circumference (NC), glucose levels, TC, TG, and the inflammatory marker TNF-α compared to the control group (Group 1)." (PMID 39149648, 2024).
metabolic syndrome (continued). "Metabolic syndrome (MetS), characterized by a cluster of metabolic dysregulations, such as abdominal obesity, hypertension, hyperglycemia, and dyslipidemia, leads to systemic low-grade inflammation primarily through the increased production of proinflammatory cytokines, such as IL-6, CRP, and TNF-α." (PMID 39452916, 2024). "Our results showed that SAR131675 treatment significantly reduced dyslipidemia and intrarenal lipid accumulation to the levels comparable to that of non-diabetic db/m mice and subsequently decreased TGF-β and TNF-α levels and oxidative stress." (PMID 30833548, 2019). "TNF-α, IL-6, and CPR more strongly correlated with arterial stiffness parameters in patients with ischemic stroke and metabolic syndrome compared to those with acute ischemic stroke but without metabolic syndrome." (PMID 34202323, 2021). "TNFα levels however were only elevated in those patients who already suffered from non-alcoholic fatty liver disease (NAFLD), although they did not discriminate between adolescents with and without aspects of metabolic syndrome or prediabetes." (PMID 28859076, 2017). "Thus, hyperinsulinemia and fasting insulin hypersecretion abated, dyslipidemia reversed, and the circulating concentrations of MCP-1 and IL-6 (but not TNFα) decreased." (PMID 28827671, 2017). "Consequently, the negative correlations of adiponectin and the adiponectin/TNF-α ratio with FBG and TG that observed in the current study could be addressed as the protective effects of adiponectin against metabolic syndrome complications in women with GDM." (PMID 29387323, 2018).